PLCG1 (phospholipase C gamma 1)
Diseases named in the same sentence as PLCG1 in open-access papers (continued):
Sharing a sentence is not in itself a finding about the gene and the disease.
gastric adenocarcinoma (3 papers, 2015 to 2017). "Our findings indicate that inhibiting PLCγ1 suppresses human gastric adenocarcinoma growth and metastasis and that the signaling molecules Akt, ERK, Bad and S6 are all involved." (PMID 26811493, 2016). "Our findings indicate that the depletion of PLCγ1 by the transduction with lentivirus-mediated PLCγ1 shRNA vector led to the suppression of tumor growth and metastasis in human gastric adenocarcinoma in vitro and in vivo." (PMID 26811493, 2016). "In conclusion, the inhibition of PLCγ1 by the transduction with Lentivirus-mediated PLCγ1 gene short-hairpin RNA vector led to the decrease of tumor growth and metastasis of human gastric adenocarcinoma in vivo and in vitro." (PMID 26811493, 2016). "The results manifested that the depletion of PLCγ1 by the transduction with lentivirus-mediated PLCγ1 gene short-hairpin RNA (shRNA) vector led to the decrease of tumor growth and metastasis of human gastric adenocarcinoma in vitro and in vivo." (PMID 26811493, 2016). "Our data also displayed that the depletion of PLCγ1 by shRNA suppressed cell proliferation and migration of human gastric adenocarcinoma cells in vitro and in vivo." (PMID 26811493, 2016). "The data indicated the existence of Akt/Bad, ERK/Bad, and Akt/S6 axes in PLCγ1-mediated tumor growth, metastasis and angiogenesis in human gastric adenocarcinoma." (PMID 26811493, 2016). "Our previous study showed that PLCγ1 is strongly expressed in human gastric adenocarcinoma tissue, and that metastasis of human gastric adenocarcinoma depends in part on PLCγ1 expression." (PMID 26811493, 2016). "The effect of inhibiting PKCδ and CaMK IIβ on PLCγ1-driven cell proliferation and apoptosis in human gastric adenocarcinoma cells." (PMID 26633375, 2015). "Here, we investigated the role of DAG/PKCδ or CaMK IIβ in PLCγ1-driven cell proliferation and migration of human gastric adenocarcinoma cells, using the BGC-823 cell line." (PMID 26633375, 2015). "Our previous study also showed the higher expression of PLCγ1 in human gastric adenocarcinoma tissue and that the metastasis of human gastric adenocarcinoma cells partly depends on PLCγ1 expression." (PMID 26633375, 2015). "Collectively, the data indicated that the blockade of DAG/PKCδ and CaMK IIβ down-regulated cell migration of gastric adenocarcinoma cells, as well as the effect of PLCγ1 inhibition." (PMID 26633375, 2015). "Our previous study indicated that the migration of gastric adenocarcinoma cells partly depended on PLCγ1 activation." (PMID 26633375, 2015). "The expression of PKCδ and CaMK IIβ in mice tumor xenograft model derived from gastric adenocarcinoma cells with the transfection of sh-PLCγ1." (PMID 26633375, 2015). "Furthermore, the phosphorylation of Akt, ERK, Bad, and S6 signaling molecules was involved in PLCγ1-mediated tumor growth and metastasis of human gastric adenocarcinoma cells." (PMID 26811493, 2016). "The data suggest that inhibiting PLCγ1 could suppress human gastric adenocarcinoma growth and metastasis, indicating that PLCγ1 is a potential target for human gastric adenocarcinoma." (PMID 26811493, 2016). "BGC-823 cell line transduced with a lentivirus-mediated PLCγ1 gene short-hairpin RNA (shRNA) vector and a nude mouse xenograft model were used to investigate the mechanism by which PLCγ stimulates growth and metastasis of gastric adenocarcinoma." (PMID 26811493, 2016). "Furthermore, the Akt/Bad, Akt/S6, and ERK/Bad signal axes were involved in PLCγ1-mediated tumor growth and metastasis of human gastric adenocarcinoma." (PMID 26811493, 2016). "Overall, the depletion of PLCγ1 by shRNA could suppress tumor metastasis in a nude mouse xenograft model of human gastric adenocarcinoma." (PMID 26811493, 2016). "Furthermore, Akt/Bad, ERK/Bad, and Akt/S6 axes were involved in PLCγ1-mediated cell proliferation and migration of human gastric adenocarcinoma cells." (PMID 26811493, 2016).
gastric adenocarcinoma (continued). "Consequently, both DAG/PKCδ and IP3/Ca2+/CaMK IIβ operate in parallel to each other in PLCγ1-driven cell proliferation and migration of human gastric adenocarcinoma cells." (PMID 26633375, 2015). "In this study, we demonstrated that the inhibition of DAG/PKCδ and CaMK IIβ could block cell proliferation and migration of human gastric adenocarcinoma cells as well as the inhibition of PLCγ1." (PMID 26633375, 2015). "Therefore, DAG/PKCδ and IP3/Ca2+/CaMK IIβ operate in parallel to each other in PLCγ1-driven cell proliferation and migration of human gastric adenocarcinoma cells." (PMID 26633375, 2015). "Therefore, it is suggested that the two classical axes of PLCγ1, DAG/PKCδ and IP3/Ca2+/CaMK IIβ, are involved simultaneously in PLCγ1-driven cell proliferation and metastasis of human gastric adenocarcinoma cells." (PMID 26633375, 2015). "Therefore, it is suggested that both DAG/PKCδ and IP3/Ca2+/CaMK IIβ operate in parallel to each other in PLCγ1-driven cell proliferation and migration of human gastric adenocarcinoma cells through Akt/mTOR/S6 pathway." (PMID 26633375, 2015). "The data suggest that the abrogation of PLCγ1 signaling by shRNA could efficaciously suppress tumor growth and metastasis of human gastric adenocarcinoma through Akt/Bad, ERK/Bad, and Akt/S6 signal axes, implying that PLCγ1 is a potential target for human gastric adenocarcinoma." (PMID 26811493, 2016). "Hence, the depletion of PLCγ1 by shRNA3 could suppress human gastric adenocarcinoma growth in a nude mouse tumor xenograft model." (PMID 26811493, 2016). "Therefore, it is suggested that the blockade of PLCγ1 could be a therapeutic approach for preventing tumor growth and metastasis in human gastric adenocarcinoma." (PMID 26811493, 2016). "Therefore, we suggested that the inhibition of PLCγ1 could suppress tumor angiogenesis in human gastric adenocarcinoma." (PMID 26811493, 2016). "Therefore, lentivirus-mediated PLCγ1 shRNAs could suppress migration of human gastric adenocarcinoma cells." (PMID 26811493, 2016). "The molecular mechanism of PLCγ1 regulating angiogenesis and EMT in human gastric adenocarcinoma needs further to be studied." (PMID 26811493, 2016). "Therefore, the abrogation of PLCγ1 signaling by shRNA could efficaciously suppress human gastric adenocarcinoma tumor growth and metastasis, with important implication for validating PLCγ1 as a potential target for human gastric adenocarcinoma." (PMID 26811493, 2016). "The depletion of PLCγ1 by shRNA3 led to the decrease in p-Akt, p-ERK1/2, p-Bad (Ser112), p-Bad (Ser136), and p-S6 (Ser235/236) levels in tumor tissue of human gastric adenocarcinoma xenografts in vivo (*P < 0.05, **P < 0.01, ***P < 0.001, vs control)." (PMID 26811493, 2016). "The expression levels of PKCδ and CaMK IIβ protein were down-regulated in mice tumor xenograft model derived from human gastric adenocarcinoma cells, BGC-823, with the transfection of sh-PLCγ1 vector." (PMID 26633375, 2015). "However, whether DAG/PKCδ and IP3/Ca2+/CaMK IIβ axes are simultaneously involved in PLCγ1-driven cell proliferation and migration of human gastric adenocarcinoma cells and the underlying mechanism are not elucidated." (PMID 26633375, 2015). "Our previous study also showed that PLCγ1 activated mTOR signalling, which is known to be a negative autophagy regulator, in gastric adenocarcinoma cells." (PMID 29066806, 2017). "On the other hand, the involvement of Akt and ERK signaling pathways in PLCγ1-mediated tumor growth and metastasis implied the existence of the crosstalk of PLCγ1 with Akt or ERK in human gastric adenocarcinoma, which has been also demonstrated in some cancer cells." (PMID 26811493, 2016). "Overall, it is confirmed that the inhibition of PLCγ1 could suppress tumor metastasis through blocking angiogenesis and EMT progression in human gastric adenocarcinoma." (PMID 26811493, 2016).
Immunodeficiency (3 papers, 2013 to 2023). Failure of the immune system to protect the body adequately from infection, due to the absence or insufficiency of some component process or substance. "One immunodeficiency affects cytosolic Mg2+ levels, required for PLCγ1 activation, via mutations in the magnesium transporter 1 (MAGT1) in patients with X-linked immunodeficiency with magnesium defect, EBV infection, and neoplasia (XMEN)." (PMID 32251475, 2020). "The other immunodeficiency is caused by mutations in the guanine nucleotide exchange factor RasGRP1, downstream of PLCγ1 signaling." (PMID 32251475, 2020).
melanoma (3 papers, 2012 to 2020). A malignant, usually aggressive tumor composed of atypical, neoplastic melanocytes. "Interestingly, the interaction network identified additional kinases that are involved in cancer progression but that have not been previously associated with melanoma, such as paxillin, PLCG1 and TEC." (PMID 32098410, 2020). "SD suppresses multiplication of melanoma B16F10 cells, diminishes permeability for Ca2+ ions and decreases protein levels of COX-2, and increases degradation of phospholipases PLA2 and PLCγ1 and diminishes enzymatic activity of the Ca2+-dependent cPLA2." (PMID 23170076, 2012).
metabolic syndrome (3 papers, 2011 to 2025). A cluster of metabolic risk factors for CARDIOVASCULAR DISEASES and TYPE 2 DIABETES MELLITUS. "For example, in a GWAS of clustering of metabolic phenotypes, PLCG1 variants were associated with metabolic syndrome." (PMID 41159936, 2025).
squamous cell carcinoma (3 papers, 2015 to 2025). A carcinoma arising from squamous epithelial cells. "PLCγ1 is required for the epidermal growth factor receptor (EGFR)-induced squamous cell carcinoma cell mitogenesis." (PMID 26633375, 2015).
virus infection (3 papers, 2017 to 2023). "Biphasic activation of PLCγ-1 signaling by BoHV-1 infection in MDBK cells corroborated the requirement of PLC signaling in the virus infection." (PMID 28882164, 2017). "In this study, for the first time we show that BoHV-1 infection manipulated phospholipase C (PLC) signaling, as demonstrated by the activation of PLCγ-1 at both early stages [at 0.5 h post-infection (hpi)] and late stages (4–12 hpi) during the virus infection of MDBK cells." (PMID 28882164, 2017).
Alzheimer disease (2 papers, 2015 to 2022). A progressive, neurodegenerative disease characterized by loss of function and death of nerve cells in several areas of the brain leading to loss of cognitive function such as memory and language. "PLCG1 (phospholipase-C gamma 1), a possible alternative to amyloid-beta targeting in Alzheimer’s disease (AD), can be modulated via PLCG1-AS, a MIR-NAT with an inverted MIRb repeat." (PMID 36250017, 2022).
colitis (2 papers, 2015 to 2018). Inflammation of the colon. "This work was designed to investigate whether the deletion of PLCγ1 in IECs could reduce colitis-associated tumor incidence (CATI) through the induction of apoptosis." (PMID 29464031, 2018). "Accordingly, the deletion of PLCγ1 in IEC reduced colitis-induced epithelial inflammation via inhibition of pro-inflammatory cytokines and mediators." (PMID 29464031, 2018). "The PLCγ1 pathway in IEC accelerated colitis-induced epithelial damage via regulation of TJ proteins." (PMID 29464031, 2018). "Here we found that PLCγ1 regulated colitis and tumorigenesis in intestinal epithelial cells (IEC)." (PMID 29464031, 2018). "To assess whether PLCγ1 may affect colonic inflammation, we applied the DSS-induced acute colitis model in PLCγ1 conditional knockout mice and their littermate controls." (PMID 29464031, 2018). "IL-6 plays important roles in tumor initiation via PLCγ1–mediated inflammatory response in colitis environment, and also after recovered colitis by removal of DSS, crosstalk between stat-3 and PLCγ1 is involved in tumor progression and development through apoptosis and proliferation." (PMID 29464031, 2018). "After three days of DSS administration, WT mice lost more body weight than did PLCγ1 conditional knockout mice, which is an induction of the severity of DSS-induced colitis." (PMID 29464031, 2018).
lupus (2 papers, 2019 to 2021). "The enzyme phospholipase C gamma 1 (PLCγ1) has been identified as a potential drug target of interest for various pathological conditions such as immune disorders, systemic lupus erythematosus, and cancers." (PMID 31548507, 2019).
metastatic disease (2 papers, 2015 to 2019). "In contrast, seven mutations were found only in the metastatic tumor, including PLCG1-R707Q missense mutation." (PMID 26474454, 2015). "Therefore, targeting the PLCγ1 pathway can be considered of potential benefit for prevention of metastatic disease." (PMID 31362705, 2019). "In contrast, seven other non-synonymous or frameshift mutations (in genes UGT3A2, PLCG1, OR10K1, COL9A1, MAGEA6, CNBD1 and LG14) were detected only in the metastatic tumor, indicating a selection and proliferative advantage of cells with the diverse genotype under sunitinib treatment." (PMID 26474454, 2015).
neuroblastoma (2 papers, 2006 to 2024). Neuroblastoma (NB) is the most common solid, extracranial childhood tumor. "We report that pre-treatment with IFN-γ increased the levels of cPLA2 in SH-SY5Y neuroblastoma cells without affecting total cellular protein concentrations, or the levels of PLCγ-1." (PMID 16569229, 2006).
prostate tumors (2 papers, 2004 to 2017). "However, RALA and PLCγ1 expression were not significantly correlated with other clinical features of the prostate tumors." (PMID 28903407, 2017).
renal cell carcinoma (2 papers, 2020 to 2021). "For example, in renal cell cancer, in addition to AKT signaling pathway, PLCγ-1, p38α, JNK, and PTEN, but not ERK1/2, were involved in CaSR-dependent bone metastasis and cellular proliferation." (PMID 32671062, 2020).
Salmonella Infections (2 papers, 2021 to 2022). Infections with bacteria of the genus SALMONELLA. "Even though we are not aware of what bacterial factors may be involved in dephosphorylating PLCG1, it is reasonable to assume that this action is part of the asymptomatic inflammatory response of chickens that leads to the development of a persistent Salmonella infection in the chicken." (PMID 35846741, 2022).
age (1 paper, 2024). A temporal measurement of the time period elapsed since an identifiable point in the life cycle of an organism. "These contradictory findings suggested that the causal role of PLCγ1 in age‐related OA did not terminate and PLCγ1 may play a unique role in the ageing process and OA pathogenesis." (PMID 39159149, 2024).
allergic reactions (1 paper, 2023). "Taken together, these results suggest that TAAR extract can effectively prevent IgE-mediated allergic reactions through the inhibition of FcεRI-mediated mast cell activation by down-regulating the phosphorylation of Lyn, Syk, Fyn, PLCγ1, and PKCδ." (PMID 37569351, 2023).
astroglioma (1 paper, 2015). "In human astroglioma cells, epigallocatechin gallate regulates phosphatidylcholine-specific phospholipase D (PLD) activity via a signaling pathway involving changes in the redox state that stimulates a PLCγ1/IP3/CaMK II/PLD and a PLCγ1/DAG/PKC/PLD axes." (PMID 26633375, 2015).
cardiac septal defects (1 paper, 2025). "Here, we describe seven individuals with heterozygous missense variants in PLCG1 [p.(Asp1019Gly), p.(His380Arg), p.(Asp1165Gly), and p.(Leu597Phe)] who present with hearing impairment (5/7), ocular pathology (4/7), cardiac septal defects (3/6), and various immunological issues (5/7)." (PMID 40862571, 2025).
colon adenocarcinoma (1 paper, 2022). "The somatic mutation of eight risk PRGs (CASP4, GPX4, GSDMC, TLR3, NLRP1, PLCG1, IL18, and IRF1) hardly occurred in PAAD samples but were commonly observed in colon adenocarcinoma (COAD) and stomach adenocarcinoma (STAD) ones." (PMID 35000541, 2022).
diabetic kidney disease (1 paper, 2020). Progressive kidney disorder caused by vascular damage to the glomerular capillaries, in patients with diabetes mellitus. "These three genes haven’t been directly associated with CKD but were implicated in IgA nephropathy (SOS1), diabetic kidney disease (MYLK), and paroxysmal nocturnal hemoglobinuria, respectively (PLCG1)." (PMID 32957963, 2020).
diabetic retinopathy (1 paper, 2022). "The events downstream of CD40 that trigger the PLCγ1–ATP–P2X7–proinflammatory cytokine cascade and promotes diabetic retinopathy are unknown." (PMID 35920844, 2022). "The molecular event downstream of CD40 that activates the PLCγ1–ATP–P2X7–proinflammatory cytokine cascade and promotes development of diabetic retinopathy is unknown." (PMID 35920844, 2022).
head and neck squamous cell carcinoma (1 paper, 2016). A squamous cell carcinoma that arises from any of the following anatomic sites: lip and oral cavity, nasal cavity, paranasal sinuses, pharynx, larynx, and salivary glands. "Furthermore, combined inhibition of PLCγ1 and c-Src abrogates EGFR-mediated head and neck squamous cell carcinoma invasion." (PMID 26811493, 2016).
Inguinal hernia (1 paper, 2020). Protrusion of the contents of the abdominal cavity through the inguinal canal. "We discovered that PIK3R1, PTPN11, TGFBR1, CDC42, SOS1, and KRAS were the most essential inguinal hernia-causative proteins and UBC, GRB2, CTNNB1, HSP90AA1, CBL, PLCG1, and CRK were listed as the most commonly-involved downstream proteins." (PMID 31910207, 2020).
Insulin resistance (1 paper, 2017). Increased resistance towards insulin, that is, diminished effectiveness of insulin in reducing blood glucose levels. "Genome loci based data and population study support that highly connected genes, like ADIPOQ, MAPK3, PLCG1 and APPL1 in the database, play an important role in insulin resistance development." (PMID 29201145, 2017).
metastatic colorectal cancer (1 paper, 2024). "Second, and in contrast, cetuximab and EGFR-targeted therapy has long been an approved treatment protocol for RAS wild-type, metastatic colorectal cancer, and SHP2 inhibitors reliant on phospholipase C gamma 1 (PLCg1) exhibit anti-tumor effects in cancer cells resistant to cetuximab." (PMID 38504984, 2024).
migraine (1 paper, 2024). "We further found drugs targeted for another six proteins (CSK, FER, GP1BA, PLCG1, PLG, and SERPING1), although currently there are no indications for migraine." (PMID 38898596, 2024).
myeloproliferative neoplasm (1 paper, 2022). A clonal hematopoietic stem cell disorder, characterized by proliferation in the bone marrow of one or more of the myeloid (i.e., granulocytic, erythroid, megakaryocytic, and mast cell) lineages. "Due to this similarity across these FGFR1 fusions, PLCγ1 inhibition may be a beneficial therapeutic target in treating FGFR1 translocation induced myeloproliferative neoplasms." (PMID 35574218, 2022).
osteosarcoma (1 paper, 2022). A usually aggressive malignant bone-forming mesenchymal neoplasm, predominantly affecting adolescents and young adults. "Moreover, PLCG1 is also involved in the B-cell receptor signaling pathway and Fc-epsilon RI signaling pathway in osteosarcoma cells." (PMID 35053609, 2022).
Parkinson disease (1 paper, 2023). A progressive degenerative disorder of the central nervous system characterized by loss of dopamine producing neurons in the substantia nigra and the presence of Lewy bodies in the substantia nigra and locus coeruleus. "Given the vulnerability of SNc dopamine neurons in Parkinson’s disease (PD) and their premature degeneration during disease progression, we hypothesized that the increased dopamine release in PLCγ1 cKO mice would attenuate the degeneration of dopamine neurons in an animal model of PD." (PMID 37907739, 2023).
periodontitis (1 paper, 2023). An acute or chronic inflammatory process that affects the tissues that surround and support the teeth. "With the exception of PLCG1, all 48 significant PRGs were significantly differentially expressed among the three PRG patterns, confirming the diversity of PRG patterns in periodontitis." (PMID 37090158, 2023).